ANGPTL2 (angiopoietin like 2)
Diseases named in the same sentence as ANGPTL2 in open-access papers (continued):
Sharing a sentence is not in itself a finding about the gene and the disease.
cancer (37 papers, 2014 to 2025). A tumor composed of atypical neoplastic, often pleomorphic cells that invade other tissues. "Angptl2 is thus better acknowledged for its association with multiple chronic diseases, in particular in various types of cancers." (PMID 34830112, 2021). "ANGPTL2 is better acknowledged for its association with multiple chronic diseases, in particular in various types of cancers." (PMID 29138671, 2017). "Certain mutations of ANGPTL2 in many human cancers may result in a marked reduction in SEV secretion, which further contributes to tumorigenesis." (PMID 37751067, 2024). "The adipokine ANGPTL2 is associated with cancer progression and metastasis." (PMID 36917086, 2023). "Both cancer and cardiovascular diseases are associated with chronic low-grade inflammation, in which sustained overproduction of proinflammatory ANGPTL2 could contribute." (PMID 29138671, 2017). "High levels of ANGPTL2 have been proposed as a biomarker of chronic inflammatory disorders and early diagnosis, prognosis, and recurrences of some types of cancers." (PMID 37189824, 2023). "In some cancer contexts, abundant expression of ANGPTL2 is highly related to the frequencies of carcinogenesis and metastasis and shortened survival periods." (PMID 35719407, 2022). "There is a significant reduction in the expression of ANGPTL1, which has anti-angiogenic properties, in favor of ANGPTL2, with pro-angiogenic properties, due to which, there is an enhanced angiogenesis supporting the development of cancer and its metastasis." (PMID 34445141, 2021). "In contrast to induction of inflammation-related genes by ANGPTL2, the roles of cell motility and MMPs in cancer progression are well documented." (PMID 32082485, 2020). "Some authors proposed the utility of detection higher serum ANGPTL2 levels in cancer patients, in particular in metastatic breast cancer patients." (PMID 29389861, 2018). "Elevated serum ANGPTL2 levels have been reported in various types of cancer, making ANGPTL2 a potential biomarker for early diagnosis, prognosis, and recurrence of cancer." (PMID 29138671, 2017). "The same team then demonstrated that integrin α5β1 binds ANGPTL2 in adipocytes, endothelial cells, and cancer cells because the effects of recombinant ANGPTL2 protein were blocked by integrin α5β1-neutralizing antibodies." (PMID 29138671, 2017). "The obvious link between an increase in circulating levels of ANGPTL2 and chronic diseases such as cancer and cardiovascular diseases is systemic inflammation." (PMID 29138671, 2017). "Cancer cells produce and secrete ANGPTL2; this was observed in breast cancer cells and in esophageal cancer cell lines." (PMID 29138671, 2017). "High circulating levels of ANGPTL2 have indeed been proposed to be a biomarker for early diagnosis and recurrence of various types of cancers." (PMID 29138671, 2017). "In addition, ANGPTL2 has been reported to be involved in pathological angiogenesis in diseases such as cancer." (PMID 40540411, 2025). "Therefore, further efforts are required to unravel the roles of ANGPTL2 mutants in ECs in the initiation and progression of different cancer types, especially through the related release of ANGPLT2-SEVs." (PMID 37751067, 2024). "It will be very important to unravel the potential functions of ANGPTL2 mutants in different types of cancers and whether these effects are dependent on the exosomal secretion of ANGPTL2." (PMID 37751067, 2024). "To investigate whether ANGPTL2 activity impacts MHC‐I expression in human cancer cells, we performed siRNA‐mediated ANGPTL2 knockdown (KD) in the human tRCC cell line UOK120, which was established from tumors of a tRCC patient." (PMID 37452654, 2023). "Angptl2 is also a biomarker for the diagnosis and prognosis of various types of cancer." (PMID 34830112, 2021). "But overall, all research data supported that ANGPTL2 may act as a critical factor in cancer development." (PMID 31384179, 2019).
cancer (continued). "In addition, abnormal expression of ANGPTL2 in various malignant tumors suggested the involvement of ANGPTL2 in cancer cell proliferation, metastasis and invasion." (PMID 31384179, 2019). "One report proposed that ANGPTL2 could be cleaved into domain fragments by the tolloid-like 1 protease and be inactivated, at least in vitro in cultured cancer cells." (PMID 29138671, 2017). "When secreted by adipocytes, endothelial cells, macrophages, cardiomyocytes, kidney cells, hematopoietic stem cells, or cancer cells, ANGPTL2 acts rather locally, exhibiting both autocrine and paracrine effects, leading to physiological and pathological effects." (PMID 29138671, 2017). "Based on the limited literature on the subject of ANGPTL2 methylation, we observe contrasting results; in cancer cells, researchers have reported a decrease in ANGPTL2 methylation resulting in an increased ANGPTL2 expression with the progression of the disease while others have shown the opposite." (PMID 27101308, 2016). "Downregulation of ANGPTL2 by siRNA reduces migration and invasion and inhibits cancer cell growth." (PMID 25370833, 2015). "Additionally, we have demonstrated that strong immunostaining of ANGPTL2 occurred in residual cancer cells in prostate specimens obtained from patients who had undergone neoadjuvant hormonal therapy." (PMID 25370833, 2015). "Furthermore, stably overexpressed ANGPTL2 promotes cancer cell growth, migration and invasion, in the general and androgen-deprived media over the long term via escape from apoptosis and promotion of EMT." (PMID 25370833, 2015). "It was also reported that ANGPTL2 increases EMT in cancer cells." (PMID 25370833, 2015). "Cancer cell-derived ANGPTL2 is an important factor in cancer development." (PMID 25370833, 2015). "The biological and clinical significance of ANGPTL2 remains unknown in human cancer." (PMID 32082485, 2020). "This may suggested that ANGPTL2 could act differently in different cancer." (PMID 31384179, 2019). "Thus, ANGPTL2 secretion from cancer cells likely contributes to MMP activity in those cells." (PMID 25773070, 2015). "Angptl2 is expressed in the heart, adipose tissue, stomach, small intestine, colon, ovary, uterus, spleen, striated muscle, and, at lower levels, in other tissues and Angptl2 is secreted by different cell types such as adipocytes, endothelial cells, macrophages, keratinocytes and cancer cells." (PMID 25077060, 2014). "Angiopoietin-like 2 (ANGPTL2), a secreted protein which belongs to the angiopoietin (ANGPTL) family, was reported to be involved in the regulation of several different type of cancer cell proliferation and metastasis." (PMID 31384179, 2019). "However, it is possible that higher circulating levels of ANGPTL2 observed in a particular disease reflect dysfunction of a specific cell type: ANGPTL2 derived from activated cancer cells may increase circulating ANGPTL2 levels, contributing to the pathogenesis of cancer." (PMID 29138671, 2017). "In contrast, ANGPTL2, BAG1, and CDH2 were mainly expressed in cancer cells and oligodendrocytes." (PMID 36291283, 2022). "Angptl2 has been listed as a member of the SASP in multiple other senescent cell types, such as fibroblasts, vascular smooth muscle cells, hepatocytes, astrocytes, platelets, and some cancers cells." (PMID 34830112, 2021). "Second, we did not determine circulating plasma levels of ANGPTL2 protein in patients with PTC or in non-cancer participants." (PMID 31384179, 2019). "According to the IHC scoring system, the mean ± SD ANGPTL2 IHC score for cancer was 105.0 ± 6.8, and the score for noncancerous tissue was 67.8 ± 6.7." (PMID 31384179, 2019). "Unlike ANGPTL1, ANGPTL2 is better acknowledged for its adverse pro-inflammatory properties and its contribution in cancer, diabetes, atherosclerosis, metabolic disorders and many other chronic diseases." (PMID 29389861, 2018).
cancer (continued). "In most cancers, the signature genes were differentially methylated compared to normal tissue; in particular, genes including as representatives NCOA4, CTSL, MCUB, ANXA5 and ANGPTL2 were usually hypermethylated, while genes including PDE2A and others were usually hypomethylated." (PMID 37660060, 2023). "Furthermore, the impact of ANGPTL2 on PTC cell proliferation, metastasis, recurrence and invasion was assessed to investigate the possibility whether ANGPTL2 may become a novel target for PTC therapy and cancer prognosis." (PMID 31384179, 2019). "Thus, we speculate that blocking ANGPTL2–integrin α5β1 signaling could antagonize development of irAEs without significantly compromising anti-cancer immunity." (PMID 37736764, 2023). "Interestingly, ANGPTL2 mRNA levels show a significant positive correlation with those of JARID2 mRNA, and levels of both are negatively correlated with those of HLA‐B and HLA‐C mRNAs in cancer lines derived from metastatic rather than primary lesions." (PMID 37452654, 2023).
cardiovascular diseases (15 papers, 2013 to 2026). "Previous studies have reported that the LILRB2 ligand ANGPTL2 is associated with cardiovascular diseases in humans." (PMID 41235141, 2025). "Interestingly, we observed that circulating levels of ANGPTL2 were associated with the cardiopulmonary function of patients with cardiovascular diseases: the better the VO2 max, the lower baseline circulating levels of ANGPTL2." (PMID 29138671, 2017). "These maladaptive effects of ANGPTL2 promote the pathogenesis of various age‐related diseases, including metabolic disorders, cardiovascular diseases, and possibly some cancers." (PMID 41508557, 2026). "Taken together, these findings suggest that disruption of circadian regulation of ANGPTL2 expression leads to chronic inflammation, resulting in development of lifestyle-related metabolic disorders and cardiovascular disease." (PMID 23469106, 2013). "Evaluation of major parameters of cardiovascular dysfunction concerning ANGPTL2 and ANGPTL3, especially in a cohort design, is highly recommended for future research to establish the connection between these markers and risk of cardiovascular diseases that generally accompany obesity." (PMID 34422408, 2021). "Furthermore, ANGPTL2 has been reported to be involved in the progression of cardiovascular diseases." (PMID 33256685, 2020). "ANGPTL2 has been proven to play an important role in the damage of vascular endothelial cells and the promotion of macrophage infiltration in atheromatous plaques, and it has become a hotspot in cardiovascular disease research." (PMID 32034642, 2020). "ANGPTL2 has been shown to contribute to the senescence-associated secretory phenotype (SASP) in aged induced pluripotent stem cells from patients with Werner syndrome, a progeria leading to premature aging, increased fat mass, and cardiovascular diseases." (PMID 29138671, 2017). "In addition, whether ANGPTL2-induced oxidative stress contributes to cardiovascular diseases and atherogenesis remains to be demonstrated." (PMID 38426206, 2024). "Thus, increased ANGPTL2 and ANGPTL3 levels in obese children and adolescents might be considered a risk factor that predisposes them to early cardiovascular disorders." (PMID 34422408, 2021).
metabolic disease (8 papers, 2013 to 2025). A congenital disorder (due to inherited enzyme abnormality) or acquired (due to failure of a metabolically important organ) disorder resulting from an abnormal metabolic process. "Serum ANGPTL2 levels are upregulated mainly in visceral obesity and related metabolic disorders." (PMID 37189824, 2023).
inflammation (4 papers, 2016 to 2023). Aberrant reaction of the microcirculation characterized by movement of fluid and leukocytes from the blood into extravascular tissues. "Acute brain inflammation after ischemia-reperfusion, as estimated by expression levels of pro-inflammatory cytokines such as interleukin (IL)-1β and tumor necrosis factor alpha (TNF)-α, was significantly suppressed in Angptl2 KO compared to control mice." (PMID 27861531, 2016).
kidney disease (4 papers, 2017 to 2024). "Altogether, these studies suggest that the kidney could be a source of ANGPTL2 and that it plays an active role in kidney disease." (PMID 29138671, 2017).
heart disease (3 papers, 2014 to 2020). "Finally, we asked whether ANGPTL2 functions in pathological cardiac remodelling by evaluating ANGPTL2 protein levels in heart tissues obtained at autopsy from patients diagnosed with chronic HF (n=3) versus individuals who died in circumstances unrelated to heart disease (n=5)." (PMID 27677409, 2016).
vasculopathy (1 paper, 2025). "In sum, our data reveal that utilization of UAS03 is an effective method for mitigating the vasculopathy induced by ANGPTL2 in vitro." (PMID 40540411, 2025). "Our data suggest that various vasculopathy-related gene expression changes mediated by ANGPTL2 are driven through β-catenin." (PMID 40540411, 2025). "Further, we assessed the necessity of ANGPTL2 in vasculopathy and fibrogenesis in the Snail-tg adult mouse in vivo." (PMID 40540411, 2025). "To test the role of ANGPTL2 in SSc vasculopathy, we generated a Angptl2-KO mouse in the Snail-tg background." (PMID 40540411, 2025). "Our work has revealed that UAS03 targets multiple pathways downstream of ANGPTL2, leading to a reduction in vasculopathy-mediated fibrogenesis." (PMID 40540411, 2025). "Overall, these data indicate that ANGPTL2 is an important factor that drives the vasculopathy and fibrotic phenotypes in Snail-tg skin." (PMID 40540411, 2025). "Our work positions ANGPTL2 secreted from Snail-tg keratinocytes as a major driver of the vasculopathy observed in fibrotic skin." (PMID 40540411, 2025). "We investigated the extent to which ANGPTL2 is sufficient to drive the vasculopathy observed in the skin of the Snail-tg mouse." (PMID 40540411, 2025). "Our investigation into the underlying mechanism of this phenotype revealed that angiopoietin-like protein 2 (ANGPTL2), secreted by the Snail transgenic keratinocytes, is a principal driver of fibrotic vasculopathy." (PMID 40540411, 2025). "ANGPTL2-mediated vasculopathy is abrogated by a synthetic analog of Urolithin A." (PMID 40540411, 2025). "We further interrogated if UAS03 could counteract the other vasculopathy defects mediated by ANGPTL2." (PMID 40540411, 2025). "Notably, these vasculopathy-related effects were abrogated when using conditioned media from Snail-tg/Angptl2-KO keratinocytes." (PMID 40540411, 2025). "Thus, ANGPTL2 is a promising early biomarker of the disease, and inhibiting the vasculopathy-inducing effects of this protein with agents such as UAS03 presents an appealing therapeutic avenue to reduce disease severity." (PMID 40540411, 2025). "We first assessed whether the presence of ANGPTL2 was required for vasculopathy-related characteristics in cultured endothelial cells." (PMID 40540411, 2025). "Therefore, we hypothesized that ANGPTL2 might also play a role in fibrotic vasculopathy in SSc skin." (PMID 40540411, 2025).
ANGPTL2 also shares sentences with these, for which no sentence is quoted: abdominal aortic aneurysm (2 papers); cervical cancer (2); chronic periodontitis (2); endometrial cancer (2); Hypertension (2); hypertriglyceridemia (2); neurodegenerative disease (2); rectal cancer (2); renal carcinoma (2); acute pancreatitis (1); artery disease (1); autoimmune disease (1); brain diseases (1); central nervous system lymphoma (1); clear cell renal cell carcinoma (1); cognitive decline (1); cognitive deficits (1); coronary artery stenosis (1); dermatitis (1); dermatomyositis (1); diffuse gastric adenocarcinoma (1); dilatation (1); esophageal squamous cell carcinoma (1); familial dilated cardiomyopathy (1); hepatitis B (1); hidradenitis suppurativa (1); Hyperglycemia (1); hyperuricemia (1); infection (1); kidney cancer (1).
A further 19 diseases each share a sentence with ANGPTL2 in 1 paper.